TNF (tumor necrosis factor)
Diseases named in the same sentence as TNF in open-access papers (continued):
Sharing a sentence is not in itself a finding about the gene and the disease.
Sepsis (continued). "Results from the current study showed that F.n. infected galectin-3−/− animals exhibited a reduction in the levels of sepsis mediators such as vascular injury markers thrombopoietin, fibrinogen, as well as acute phase protein CRP and inflammatory cytokines such as TNF-α, IL-6 and IL-1." (PMID 23527230, 2013). "In contrast to TNF-α and IL-1, the injection of IL-6 by itself does not produce a sepsis-like state." (PMID 23853427, 2013). "TNF-α showed transient significant elevation in nonsurvivor sepsis and SIRS patients in comparison to survivors." (PMID 24175285, 2013). "It has been recently found that dexmedetomidine reduces systemic levels of interleukin- 6 (IL-6), tumor necrosis factor α (TNF-α) and high mobility group box 1 (HMGB1) following lipopolysaccharide infusion or sepsis in animals, indicating its anti-inflammatory effects against renal I/R injury." (PMID 23759023, 2013). "The small proportion of sepsis patients with detectable levels of TNFα is likely to be due to the fact that samples were taken with relation to the time of admission to ICU rather than the onset of sepsis." (PMID 23531337, 2013). "In sepsis group, the admission mean values of TNF-α in survivors revealed nonsignificant change to admission mean value in nonsurvivors (P = 0.435)." (PMID 24175285, 2013). "In clinical trials targeting proinflammatory cytokines, such as TNF-α or IL-1β, in patients with sepsis have not yielded the desirable outcomes." (PMID 23533310, 2013). "Release of cytokines (IL1β, IL-6, and TNFα), nitric oxide, endotoxins, and activation of caspases (caspases 3) in setting of a gram negative bacteremia and sepsis leading to myocardial depression and ventricular dilatation is another theory to explain SRTE." (PMID 23691359, 2013). "We identified MMP13 as an important mediator in sepsis and IBD via the shedding of TNF." (PMID 23723167, 2013). "In septicemia induced by the administration of lipopolysaccharide in mice, KYNA significantly reduced the mortality rate of the animals and inhibited nitric oxide, as well as increased tumor necrosis factor α concentration." (PMID 22915278, 2013). "In sepsis patients Trem-1 expression on neutrophils shows a negative correlation to the serum levels of TNF-α (r = −0,63; p < 0,005), IP-10 (r = −0,5; p < 0,035) and procalcitonin (r = −0,59; p < 0,007)." (PMID 23414215, 2013). "This study demonstrated that non-selective beta-blockade decreased TNF-α levels both in plasma and in lung tissue at 24 hours post-induction of sepsis." (PMID 24020447, 2013). "Ketamine possesses strong anti-inflammatory properties and is able to reduce serum TNF-α after sepsis in a murine laparoscopic model, an effect not readily expected from ketamine’s action on the NMDA receptor." (PMID 23936499, 2013). "In patients with chronic inflammatory diseases, but not in patients with sepsis, there was a considerable success with the administration of anti-TNF antibodies or soluble TNF receptors in order to inhibit TNF activity." (PMID 24371374, 2013). "While inhibiting proinflammatory cytokines such as Tumor-Necrosis Factor-α (TNF) has been shown to effectively improve survival in several animal models of sepsis, anti-TNF therapy in septic humans failed to ameliorate or even worsened clinical outcome." (PMID 22518344, 2012). "Proinflammatory cytokines IL-6 and TNF-α in BALF also decreased after blockade of IL-17A intraperitoneally, indicated that anti-IL-17A antibody treatment suppressed proinflammatory response in sepsis induced lung injury." (PMID 23056325, 2012). "Association analysis of SNPs in TNF, LTA, TNFRSF1A and TNFRSF1B between survivors and non-survivors of severe sepsis patients." (PMID 23029405, 2012). "One interesting notion is that inhibition of TNF alone does not reduce complement activation during sepsis, as demonstrated in a baboon model." (PMID 23049598, 2012).
Sepsis (continued). "Therefore, is it possible that TNFα/NF-κB/NGAL is an important mechanism for regulating tubular cells by increasing proliferation and/or inducing/suppressing apoptosis during sepsis?" (PMID 22564340, 2012). "Both models of sepsis markedly increased plasma levels of TNF-α and IL-6, without statistically significant intergroup differences." (PMID 22030145, 2011). "In this work, the capacity to produce IL-12 and TNF-α from PBMCs of patients with severe sepsis was diminished, whereas the release of IL-10 was not affected." (PMID 21939530, 2011). "Thus, in patients with sepsis, and who fail to recover from sepsis, PBLs produce less of the effector cytokines that enhance phagocytic bactericidal activity such as IFN-γ and TNFα." (PMID 21711552, 2011). "Hence, circulating levels of procalcitonin, C-reactive protein, interleukin (IL)-1, IL-6, IL-8, IL-10, tumor necrosis factor alpha (TNF-α), Fas-ligand, and monocyte chemoattractant protein 1 (MCP-1) have all been highlighted as potential markers of sepsis." (PMID 22220196, 2011). "To determine if IRAK-M contributed to sepsis-induced suppression of inflammatory genes, we isolated PM from WT and IRAK-M−/− mice 24 hrs after sham surgery or CLP, then assessed for constitutive and LPS-stimulated expression of TNF-α and iNOS mRNA." (PMID 20585389, 2010). "CRP, leptin, IL-6 and TNF-α were compared among the following groups: sepsis group (n = 40), SIRS group (n = 34) and non-SIRS group (n = 32)." (PMID 20230641, 2010). "In the present analysis, we aim to investigate the “in vivo interplay” between monocytic function (assessed using monocytic HLA-DR expression [mHLA-DR] and ex vivo TNF-alpha release) and HMGB-1 serum levels in patients with severe sepsis/septic shock and sepsis-induced immunosuppression." (PMID 20652004, 2010). "Intriguingly, elevated α-MSH levels were observed particularly in non-progressive HIV patients and in sepsis patients with lower plasma tumor necrosis factor-α (TNF-α) levels." (PMID 20731841, 2010). "A positive correlation was found among leptin, IL-6 and TNF-α in both SIRS and sepsis groups." (PMID 20230641, 2010). "Major proinflammatory cytokines produced during an infection, including tumor necrosis factor (TNF)-α, interleukin (IL)-1β, interferon (IFN-γ), and IL-12, play a prominent roles in defective activation of the host immune response and sepsis-induced tissue injury." (PMID 19652714, 2009). "The systemic inflammatory response as measured by systemic release of TNF-alpha was not influenced in the Sepsis + TEA group." (PMID 19594914, 2009). "TNF-α levels are not suppressed after 48 hours but remain equal in sepsis and sham groups without medication." (PMID 19594900, 2009). "Besides, it has already been shown that endogenous TNF-α production, as well as therapeutic TNF-α substitution, have beneficial effects during sepsis of different origins." (PMID 19594900, 2009). "High concentrations of TNF-α are found in BAL fluids from patients with sustained ALI and ARDS, and high levels of IL-6 have been described in a number of acute conditions such as burns, major surgery and sepsis." (PMID 19799777, 2009). "However, SAA, PCT, TNF-α, IL-1β, and CRP were serially measured on days 0, 4, and 8 in the patients and once in the controls.Töllner's sepsis score (TSS) was calculated for each patient." (PMID 19043563, 2008). "Appearing relatively early in the circulation, TNF plays a protective role in sepsis, and its circulating levels do not correlate with lethality of experimental sepsis." (PMID 17987129, 2007). "It is not surprising that the inhibitory effect on TNF-α production is not strictly correlated with survival rate since TNF-α is not the sole mediator of lethality in severe sepsis." (PMID 17477857, 2007). "At the time of diagnosis, IL-1β, IL-6, IL-8, and TNF-α levels of culture-proven sepsis and culture-negative sepsis were significantly higher than levels at the seventh day after antibiotic treatment." (PMID 18274637, 2007).
Sepsis (continued). "Attime of diagnosis, serum IL-1β, IL-6, IL-8, and TNF-α levels of culture-provensepsis and culture-negative sepsis were significantly higher than levels atseventh day after antibiotic treatment (P<.05)." (PMID 18274637, 2007). "Since TNF, IL-1, IL-6 and MIF are all highly expressed in falciparum malaria, it can be expected that these cardiac-depressing activities would be acting in this disease as well as in sepsis." (PMID 17029647, 2006). "In a mouse sepsis model induced by APEC and MRSA, A7 treatment significantly improved survival rates (60-80%), reduced bacterial loads in vital organs, and attenuated the systemic cytokine storm (TNF-α and IL-1β), thereby alleviating immune-mediated tissue damage." (PMID 41977454, 2026). "On the one hand, statins executed anti-inflammatory effects by modulating upstream intracellular signaling pathways, on the other hand, cytokines such as TNF, IL-1β, and IL-6, were pivotal in the manifestation of SIRS and might serve as prognostic biomarkers in sepsis." (PMID 39927168, 2025). "In addition, the levels of fecal calprotectin and TNF-α were significantly higher in patients in the SAE group than in the non-SAE sepsis group, which was mirrored by the mortality rate." (PMID 40529149, 2025). "In the present study, we find that CD69 expression correlates both with cytokines stimulating MAIT cell activation and with cytokines produced by MAIT cells, such as IFNγ and TNF, which may indicate that MAIT cells contribute to the pro‐inflammatory cytokine response in sepsis." (PMID 40041474, 2025). "However, clinical trials targeting the well-known mediators associated with the response to sepsis, such as PAMPs, endotoxins, and inflammatory cytokines (e.g., IL-6, IFN-gamma, TNF, IL-1beta) have shown discrete or no efficient results." (PMID 40241761, 2025). "Additionally, even though TNF-α and IL-1β are well-known biomarkers for sepsis and VAP, previous studies did not evaluate their values at baseline, meaning the first day of intubation, but instead after a few days under mechanical ventilation." (PMID 40142568, 2025). "In lipopolysaccharide (LPS)-induced sepsis models among animals, exogenous administration of LPA or LPA receptor agonism suppresses the release of proinflammatory factors, including interleukin-6 (IL-6), tumor necrosis factor-alpha (TNF-α), and monocyte chemoattractant protein-1 (MCP-1)." (PMID 41567194, 2025). "In addition, levels of kidney function indicators (BUN and Scr) and proinflammatory factors (TNFα and IL-1β) were found to be increased in sepsis patients with AKI compared to those without AKI." (PMID 41406481, 2025). "Furthermore, total bile acid, interleukin (IL)-6, and tumor necrosis factor-α concentrations were downregulated after FXR activation, whereas IL-10 concentration was upregulated, indicating the alleviated effect of FXR agonist in sepsis." (PMID 40192065, 2025). "In the early stage of sepsis, the upregulation of CREB5 may enhance the transcriptional activity of inflammatory factors such as IL-6 and TNF-α by directly binding to the promoter region of inflammatory factors, thus driving the inflammatory response of CD16+ monocytes." (PMID 41246299, 2025). "In a prospective study targeting patients with sepsis-induced AKI, RAGE levels demonstrated a positive correlation with E-selectin (r = 0.88), endothelin-1 (ET-1) (r = 0.90), and tumor necrosis factor-α (TNF-α) (r = 0.94) levels, while being inversely correlated with NO levels." (PMID 40077627, 2025).
Sepsis (continued). "In an LPS sepsis model utilizing THP-1 cells as a monocyte surrogate, we demonstrated that minocycline dose-dependently inhibited the production of inflammatory cytokines such as TNF-α, interleukin (IL)-6, and IFN-γ, as well as chemokines including IL-8 and interferon-inducible protein (IP)-10." (PMID 41142251, 2025). "In our model, septic DM mice exhibited trends toward elevated levels of pro‐inflammatory markers, including IL‐12B, CXCL‐1, and TNF‐α, and reduced IL‐4 levels compared to mice with sepsis or DM alone; however, these differences did not consistently reach statistical significance." (PMID 40654181, 2025). "Combined effect of eleven studies (111 animal) investigating the effect of MSC-sEVs on TNF-α showed that MSC-sEVs are potent to reduce the TNF-α level compared to sepsis induced animals with no interventions (SMD: −5.23, 95% CI: −7.05, −3.41, P < 0.001; I2 = 78.7%; P < 0.001)." (PMID 41394125, 2025). "In our LPS-induced sepsis model, the CL-treated mice reconstituted with SLC25A33-silenced BMDMs exhibited a higher survival rate and decreased secretion of pro-inflammatory cytokines, such as TNF-α, IL-6, and IL-1β, relative to mice reconstituted with vehicle-treated BMDMs." (PMID 40384854, 2025). "Anti-inflammatory therapies, such as IL-6 and TNF-α inhibitors, show promise in mitigating inflammation, while immune checkpoint inhibitors like anti-PD-1 and anti-CTLA-4 antibodies are being explored to restore immune function in sepsis and enhance antitumor immunity in cancer." (PMID 40563999, 2025). "In LPS-induced sepsis rat model, PF pretreatment inhibited PI3K/Akt/ERK-mediated HIF-1α and TLR4/MyD88/NF-κB signaling, thereby reducing inflammation by decreasing the levels of tumor necrosis factor-α (TNF-α) and interleukin-1β (IL-1β) in serum and cardiac tissue." (PMID 41311552, 2025). "However, despite initial optimism, these trials failed to conclusively demonstrate the efficacy of TNF-α inhibition in sepsis treatment." (PMID 39056754, 2024). "In sepsis-induced lung injury, it is crucial to recognize the importance of inflammatory signaling pathways, specifically the Mitogen-activated protein kinases (MAPK) and NF-κB pathways, in the excessive release of inflammatory cytokines like Tumor necrosis factor alpha (TNF-α) and IL-1β." (PMID 39867697, 2024). "The lipopolysaccharide infusion induced sepsis-like inflammation with tachycardia, elevated pulmonary pressure, elevated lactate level, as well as elevated pro-inflammatory cytokines like interferon (IFN)-γ, interleukin (IL)-1β, IL-2, IL-6, IL-8, IL-12 and tumor necrosis factor alpha (TNF-α)." (PMID 39273234, 2024). "In sepsis, the mitogen-activated protein kinase (MAPK) pathway is consistently activated in conjunction with the NF-κB pathway, either independently or cooperatively stimulating the secretion of downstream inflammatory factors such as COX-2, TNF-α, IL-1β, IL-18, IL-6, and iNOS." (PMID 39267971, 2024). "To investigate whether the anti-PD-L1 antibody affected monocyte function, we selected three important cytokines, IL-6, IL-10, and TNF-α, used ELISA to assess cytokine production in the CLP-induced sepsis model and anti-PD-L1 antibody-treated septic mice at 24, 48, and 72 h." (PMID 37776443, 2024). "Furthermore, in sepsis-induced chronic lung injury in male albino mice models subjected to CLP, it was found that curcumin decreased inflammatory expression of IL-8, TNF-α, MIF in the bronchoalveolar fluid, and pulmonary edema and, as a whole, attenuated chronic lung injury." (PMID 39126050, 2024). "Additionally, we analyzed the predictive efficacy of these predictors and found that the combination of MPO and HOCl with TNF-α, WBC, and APACHE II score could better predict the occurrence of NOAF in sepsis." (PMID 39030470, 2024).
Sepsis (continued). "D-gal also worsens cecal ligation and puncture (CLP) sepsis severity when compared with PBS-CLP mice, as indicated by serum creatinine (Scr) and alanine transaminase (ALT), but not mortality, neurological characteristics (SHIRPA score), and serum cytokines (TNF-α and IL-6)." (PMID 39423218, 2024). "A longitudinal study of extremely low birth weight (<1,000 g) measured cytokines at days 1, 3, 14, and 21 after birth and found that IFN-γ, IL-10, IL-18, TGF-β, and TNF-α levels differed among infants who developed fungal or bacterial LOS compared with those who never developed sepsis." (PMID 38312920, 2024). "The cytokine response to exercise is not preceded by an increase in plasma-TNF-α as in sepsis." (PMID 39298039, 2024). "Additionally, the blockade of APOH after CLP led to a significant increase in the levels of serum and peritoneal inflammatory cytokines, such as TNF-α, IL-1β, and IL-6, alongside a decrease in IL-10 levels after non-severe sepsis." (PMID 38291524, 2024). "Another study revealed that naringenin protects against sepsis-related lung damage through AMPK-activating transcription factor 3 (ATF3)-dependent negative regulation of the LPS/TLR4 signaling pathway, suppressing the expression of TNF-α, IL-6, TLR4, iNOS, cyclo-oxygenase-2 (COX2), and NOX2." (PMID 39126050, 2024). "Alongside these findings, the trial of the TNF-α mAb afelimomab, known as the RAMESES study, provides a nuanced perspective by demonstrating a modest but significant reduction in 28-day mortality in sepsis patients with IL-6 serum levels higher than 1000 pg/mL." (PMID 39056754, 2024). "Similarly, treatment with Ginsenoside Rb1 or fisetin (a natural flavonoid) mitigates the LPS-induced kidney damages by inhibiting IL-6, TNF-α, COX-2 expression, AKT activation and prevents from sepsis-mediated death in mice by down-regulating the MAPK signaling." (PMID 39267971, 2024). "Interestingly, the induction of immune cell apoptosis sepsis of mice is facilitated by FasL rather than by endotoxins or TNF-α." (PMID 39267971, 2024). "Under the intervention of DXM, the levels of serum TNF-α, MIP-1α, SCR, BUN, NO and the ratio of lung W/D decreased, and the pathological changes of lung and kidney were alleviated, which showed that DXM played an anti-inflammatory role in sepsis and alleviated sepsis-induced lung and renal injury." (PMID 39178201, 2024). "While proinflammatory cytokines and chemokines, such as IL-6, TNFα, MCP-1, and IL-8, peak between 2–4 h after the introduction of inflammatory stimuli, SAA expression in plasma peaks at ~48 h after the induction of sepsis during the resolution phase of acute inflammation." (PMID 38139330, 2023). "Interestingly, we found that carvacrol prevents elevations in the levels of the inflammatory cytokines IL-6 not TNF-α in serum and peritoneal lavage and protects organs from damage in a murine model of LPS-induced sepsis." (PMID 37550359, 2023). "Recent studies have revealed that hepatic macrophages can secrete distinct sets of cytokines and chemokines, including TNF-α, IL-1β, and IL-6, which are the key mediators in systemic inflammatory response syndrome (SIRS) and the generation of hepatic acute-phase proteins during sepsis." (PMID 36768433, 2023). "However, clinical trials have shown that blocking TNF-α is harmful rather than beneficial in patients with sepsis, suggesting that other proinflammatory factors induced by MRP8/14 are critical for organ injury in endotoxemia." (PMID 37701855, 2023). "Administration of IL-1β-preconditioned UC-MSCs led to decreased serum levels of IL-6, TNF-α, alanine aminotransferase and aspartate aminotransferase, and liver, lung, and kidney injury and increased bacterial clearance and survival in experimental CLP-induced sepsis." (PMID 37007034, 2023).